NFATC1 (nuclear factor of activated T cells 1)
Diseases named in the same sentence as NFATC1 in open-access papers (continued):
Sharing a sentence is not in itself a finding about the gene and the disease.
glioma (3 papers, 2019 to 2021). A benign or malignant brain and spinal cord tumor that arises from glial cells (astrocytes, oligodendrocytes, ependymal cells). "Our data suggest a synergistic effect of DYRK1A and NFATC1 on glioma cell migration and tumor metastasis." (PMID 34309232, 2021). "All glioma cells showed high levels of NFATc3, while NFATc1 and NFATc2 expression levels were variable among the cells." (PMID 34443374, 2021). "Protein levels of DYRK1A and NFATC1 were examined in normal tissues and gliomas of different grades using tissue arrays and IHC analysis." (PMID 34309232, 2021). "Our results show that inhibition of DYRK1A by NFATC1‐P3 polypeptides significantly destabilizes NFATC1 protein levels and reduces T98G glioma cell migration." (PMID 34309232, 2021). "Correlated expression of DYRK1A and NFATC1 proteins was observed in both glioma tissues and glioma cell lines." (PMID 34309232, 2021). "Although we found that NFATc3 is the major member expressed in glioma cells we wanted to evaluate if NFATc1 has a role for the expression of these cytokines." (PMID 31249342, 2019). "To examine whether NFATC1 is affected by DYRK1A in glioma cells, we measured the protein levels of NFATC1 in T98G cells." (PMID 34309232, 2021). "High NFATC1 expression was also observed in grade 4 gliomas." (PMID 34309232, 2021). "NFATC1 expression was also correlated with DYRK1A expression in glioma cell lines." (PMID 34309232, 2021). "We propose that the recovery of NFATC1 stability is a key oncogenic event in a large proportion of gliomas, and pharmacological inhibition of DYRK1A by polypeptides could represent a promising therapeutic intervention for GBM." (PMID 34309232, 2021). "We propose that the recovery of NFATc1 stability is a key oncogenic event in a large proportion of gliomas and polypeptide pharmacological inhibition of DYRK1A could represent a promising therapeutic intervention for NFATc1‐dependent GBM." (PMID 34309232, 2021). "Moreover, DYRK1A and NFATC1 synergistically increased T98G glioma cell migration." (PMID 34309232, 2021). "Our data demonstrate that NFATC1 and DYRK1A proteins are highly expressed in gliomas, particularly in grade 4 gliomas (GBM)." (PMID 34309232, 2021). "Our results provide some support for the function of NFATC1 in GBM, and further studies are needed to determine the expression levels of all NFAT family members in glioma as well as their functions and mechanisms in tumorigenesis and tumor migration." (PMID 34309232, 2021). "Higher expression of NFATC1 and DYRK1A proteins was also observed in several glioma cell lines." (PMID 34309232, 2021).
Hyperglycemia (3 papers, 2018 to 2020). An increased concentration of glucose in the blood. "Further experiments suggested that NFATc1 siRNA mimicked the effect of TAC, whereas transfection of the TRPC6 overexpression plasmid blocked the effect of TAC on tubular inflammation under hyperglycaemia." (PMID 32779844, 2020). "In conclusion, this study delineated that TAC has a potential effect on the amelioration of tubuloinflammation and fibrosis, partially through NFATc1/TRPC6, which provides more evidence for the renoprotective effects of TAC under hyperglycaemia." (PMID 32779844, 2020).
inflammatory bowel disease (3 papers, 2015 to 2021). A spectrum of small and large bowel inflammatory diseases of unknown etiology. "The transcription factor NFATc1 was reported to play an essential role in the pathogenesis of inflammatory bowel disease and augment a number of inflammation-associated genes." (PMID 26652024, 2015).
lymphopenia (3 papers, 2016 to 2022). Reduction in the number of lymphocytes. "Hematopoietic defects due to lack of NFATc1 activity can lead to severe pathologies such as lymphopenia, myelopenia, and a drastically reduced lifespan underlining the critical role NFATc1 plays in HSPC maintenance and in the differentaion of various lineages." (PMID 35805096, 2022). "Overall, deficiency in NFATc1 activity arrested the pro-B cell transition to the pre-B cell stage, leading to severe B cell lymphopenia." (PMID 29907883, 2019). "In summary, our study underlines the essentiality of an optimal level of NFATc1 activity for B cell development and for preventing B cell lymphopenia." (PMID 29907883, 2019). "The functional significance of NFATc1 in these cells was clearly demonstrated by the B cell lymphopenia observed in Vav-CreNfatc1fl/fl mice." (PMID 29907883, 2019). "Additionally and stressing the importance of a threshold level of NFATc1 activity during a stage-specific differentiation of B cells, increased NFATc1 levels via the co-expression of NFATc1α along with NFATc1β in pro-B cells led to severe B cell lymphopenia." (PMID 29907883, 2019). "The elucidation of the signalling pathways regulating Nfatc1 gene regulation will help to better understand T-cell development and will provide insight for therapeutic manipulations of NFATc1 activity to achieve immune reconstitution in situations like T-cell lymphopenia." (PMID 27312418, 2016).
Osteochondroma (3 papers, 2018 to 2023). A common, benign cartiliginous neoplasm arising from the metaphysis of bone. "Inactivation of NFATc1 in these progenitor cells has also been shown to cause abnormal cartilage to form, a condition termed osteochondromas." (PMID 36790146, 2023).
osteosclerosis (3 papers, 2023 to 2025). Abnormally high bone density. "Mice deficient in NFATc1 cannot degrade primary spongiosa due to increased bone mass, leading to calcified cartilage build-up and severe osteosclerosis." (PMID 37993937, 2023). "Moreover, NFATc1 is a key nuclear transcription factor that regulates osteoclast differentiation and subchondral osteosclerosis in OA." (PMID 40159624, 2025). "As c-fos is a crucial mediator in osteoclast formation, required for the induction of NFATc1 nuclear factor, mice lacking c-fos develop osteosclerosis due to the obstruction of osteoclast differentiation." (PMID 39278948, 2024).
ovarian carcinoma (3 papers, 2020 to 2021). A malignant neoplasm originating from the surface ovarian epithelium. "Li and colleagues showed that in ovarian cancer cells, NFATc1 knockdown inhibits cell proliferation and migration." (PMID 33962392, 2021). "For example, Li, Duan, Yu, and Dang (2016) indicated that NFATc1 silencing regulates the cell cycle, apoptosis, invasion and migration of ovarian cancer cells." (PMID 31823518, 2020). "The expression level of NFATC1 was decreased in HCC tissues and was significantly upregulated in ovarian cancer." (PMID 32963532, 2020).
psoriasis (3 papers, 2016 to 2024). An autoimmune condition characterized by red, well-delineated plaques with silvery scales that are usually on the extensor surfaces and scalp. "A significant elevation of these cells seems to be controlled by NFATc1, a transcription factor that controls the activity of IL‐10 production in psoriasis‐like skin inflammation." (PMID 39261978, 2024). "In T cells, NFATc1 stimulates the expression of several genes that are highly expressed during psoriasis, as the Ccl3 and Ccl4 chemokine genes." (PMID 27222343, 2016).
thymoma (3 papers, 2014 to 2022). A neoplasm arising from the epithelial cells of the thymus. "In spite of the tight assembly of TF binding sites within the P1 promoter, when transfected into EL-4 thymoma cells, P1-directed luciferase reporter constructs showed a poor induction, which differs markedly from the induction of endogenous Nfatc1 gene." (PMID 24550910, 2014). "Also, it is reported that NFATc1 isoforms c1/C can be highly SUMOylated in thymoma cells." (PMID 35484132, 2022). "On stimulation with PMA+Ionomycin (I), in EL-4 thymoma cells the E2, but not the E1 element induced a strong Nfatc1 P1 promoter activity compared with a mild increase in P2 promoter activity." (PMID 27312418, 2016). "Instead of being induced as the endogenous Nfatc1 gene by the phorbol ester TPA and the Ca++-ionophore ionomycin (which mimic immune receptor signals), inducers of protein kinase A, such as forskolin, led in combination with ionomycin to the strongest induction of P1 in EL-4 thymoma cells." (PMID 24550910, 2014).
urothelial carcinoma (3 papers, 2015 to 2019). A malignant neoplasm derived from the transitional epithelium of the urinary tract (urinary bladder, ureter, urethra, or renal pelvis). "Strong NFATC1 expression was also found to be significantly associated with worse patient outcomes in urothelial carcinoma." (PMID 30901947, 2019). "We previously reported the anti-tumorigenic and oncogenic activity of NFAT in urothelial carcinoma and noted, in particular, that NFATc1 has a key role in its progression." (PMID 30400941, 2018). "We first examined the expression of NFATc1 in human urothelial carcinoma cell lines, UMUC3, TCCSUP, 647V, and 5637, and an immortalized human normal urothelial cell line, SVHUC, by western blotting and reverse transcription (RT)-polymerase chain reaction (PCR)." (PMID 25638160, 2015).
allergic asthma (2 papers, 2019 to 2020). A asthma with a basis in a pathological type I hypersensitivity reaction. "In addition to NFATc1 and NIP45, also NFATc2 was found upregulated in PBMCs and peripheral blood cells from asthmatic children and adults with allergic asthma." (PMID 33079489, 2020). "In addition, we tried to shed light on the relationship between NFATc1 and NFATc2 and IRF4, another transcription factor upregulating cytokines like IL‐4 and IL‐9 involved in allergic asthma." (PMID 33079489, 2020).
Alzheimer disease (2 papers, 2025). A progressive, neurodegenerative disease characterized by loss of function and death of nerve cells in several areas of the brain leading to loss of cognitive function such as memory and language. "Specifically, RASGRP1, PRKCB, and NFATC1 are implicated in both RA and Alzheimer’s disease, suggesting therapeutic convergence." (PMID 40839671, 2025). "In Alzheimer’s disease (AD) patients, circPSEN1 is significantly up-regulated, promoting amyloid-β (Aβ) production by inhibiting miR-137 expression and activating the nuclear factor of activated T cells 1 (NFATC1) and epidermal growth factor receptor (EGFR) pathways." (PMID 40801613, 2025).
anemia (2 papers, 2018 to 2023). A reduction in the number of red blood cells, the amount of hemoglobin, and/or the volume of packed red blood cells. "Here we show that an enhanced NFATc1 activity induced by increased integrin-cAMP signaling plays a critical role in the dysregulation of Klf1 expression and thereby cause anemia in Il2-/- mice." (PMID 29515759, 2018). "Conventional Nfatc1 whole KO mice showed anemia at E12.5, abnormal heart valve development, and died by E14.516,17." (PMID 37914750, 2023).
aortic valve disease (2 papers, 2018 to 2022). "Alternative Cre drivers, such as Periostin or Nfatc1, that target VICs at different developmental time points, including cells not derived from the Tie2 lineage, may further clarify the contributions of RB1 to aortic valve disease." (PMID 29304157, 2018). "The obtained caAcvr1:Nfatc1 mutants that were homozygous for Enpp1 (Enpp1−/−) died in utero, and thus could not be used to study the progression of aortic valve disease, while caAcvr2:Nfatc1:Enppi+/− mice were phenotypically indistinguishable from their caAcvr1:Nfatc1Cre littermates." (PMID 36005436, 2022).
apical periodontitis (2 papers, 2019 to 2023). "Cells positive for Btk, PLCγ2, and NFATc-1 were stained dark brown as shown by immunohistochemistry and were expressed in apical periodontitis at 0 to 4 weeks in experimental mice." (PMID 31427888, 2019). "It was found that the expression of Btk, PLCγ2, and NFATc-1 changed significantly with the progression of inflammation and bone destruction, indicating that Btk and PLCγ2 may be involved in the progression of inflammation in apical periodontitis and bone absorption." (PMID 31427888, 2019).
atopic dermatitis (2 papers, 2019 to 2025). "A recent study further demonstrated that NFATc1-deficient B cells ameliorate atopic dermatitis-associated allergic responses by significantly increasing IL-10-producing regulatory B cells." (PMID 40943049, 2025). "NIP45 was found significantly induced in asthmatic pre-school children with self-reported atopic eczema and positive skin test (respectively), similarly to what we recently reported for NFATc1 expression in these cohorts of children." (PMID 31666531, 2019).
cardiomyopathies (2 papers, 2017 to 2025). "More studies are needed to validate these findings in large mammalian animal models and to develop NFATC1 nuclear translocation-targeted therapeutic strategies for TNNI3K gene mutation-based cardiomyopathy and CCD." (PMID 39926332, 2025). "Given that OBCSN mutations have not been linked to CHD, but could be potentially causing cardiomyopathies, we hypothesize that the NFATC1 missense variant along the FOXC1 variant is responsible for the cardiac phenotype." (PMID 28979898, 2017). "In conclusion, we generated a unique zebrafish animal model of TNNI3K splicing mutation-based cardiomyopathy and CCD and identified the focal adhesion pathway and Mypt1/Mlc2/Yap1/Nfatc1 axis as the downstream phosphorylation targets of the Tnni3k protein." (PMID 39926332, 2025). "We found that pharmacological inhibition of the translocation of Nfatc1 into the nucleus partially alleviated the cardiomyopathy phenotypes in the heterozygous tnni3k splicing mutant zebrafish model." (PMID 39926332, 2025).
experimental autoimmune encephalomyelitis (2 papers, 2016 to 2018). An autoimmune demyelinating disease of the central nervous system that is produced experimentally in animals by the injection of homogenized brain or spinal cord in Freund's adjuvant. "In experimental autoimmune encephalomyelitis as an animal model of MS, deficiency of Nfatc1 and/or Nfatc2 ameliorated demyelination suggesting that blocking NFAT activity might be a treatment strategy in MS37." (PMID 29500351, 2018).
gastric cancer (2 papers, 2020 to 2025). A primary or metastatic malignant neoplasm involving the stomach. "Although recent research has shown that NFATc1 enhances glycolytic metabolism to fuel gastric cancer progression, its broader impact on other critical metabolic pathways, particularly the PPP, remains elusive." (PMID 41203626, 2025). "Consistently, in CRC HT29 and gastric cancer HGC-7901 cell lines, knockdown NFATc1 simultaneously suppressed the transcriptional activity of MDM2." (PMID 41203626, 2025). "Consistently, in CRC HT29 and gastric cancer HGC-7901 cell lines, NFATc1 knockdown significantly reduced the transcriptional activity of NADK." (PMID 41203626, 2025).
hypothyroidism (2 papers, 2025). Abnormally low levels of thyroid hormone. "In comparison, pLoF variants in NFATC1 (MAF < 0.001%—OR = 4.36, 95% CI = 2.11–8.99, P = 6.7 × 10−5) were associated with higher effect compared to TSHR pLoF variants, suggesting a potential monogenic role in hypothyroidism." (PMID 41238958, 2025).
ischemia (2 papers, 2021 to 2022). A hypoperfusion of the BLOOD through an organ or tissue caused by a PATHOLOGIC CONSTRICTION or obstruction of its BLOOD VESSELS, or an absence of BLOOD CIRCULATION. "In contrast to the control group (10% FBS treatment alone), the serum insufficiency (0.1% FBS) and ischemia groups did not exhibit increases in CTSK or NFATc1 expression; only RANKL stimulation increased the expression levels of both proteins." (PMID 34204469, 2021).
lupus nephritis (2 papers, 2018 to 2023). Glomerulonephritis in the context of systemic lupus erythematosus. "Sixty-six SNPs in the NFATC1 region were examined for association with lupus nephritis." (PMID 29953444, 2018). "We also found evidence of a potential association of SNP rs8091180 in the NFATC1 gene with lupus nephritis, which was strongest in for African-Americans and has not been previously associated with LN or SLE." (PMID 29953444, 2018).
Obesity (2 papers, 2016). Accumulation of substantial excess body fat. "This pathway included genes upregulated in IB piglets, which were involved in adipogenesis and in the development of obesity, as NFATC1 and PLCD1." (PMID 27936208, 2016). "In particular, the bone microenvironment can be modulated by various factors including aging, obesity, and inflammation, so RCANs effects on calcineurin-NFATc1 signaling may be dependent on these changes." (PMID 27917924, 2016).
oral squamous cell carcinoma (2 papers, 2022). "We previously observed a novel osteoclastogenesis system that is induced by oral squamous cell carcinoma (OSCC) cells, which target osteoclast precursor cells (OPC) without upregulation of the master transcriptional factor of osteoclastogenesis, NFATc1." (PMID 36614130, 2022).
osteomyelitis (2 papers, 2019 to 2024). An acute or chronic inflammation of the bone and its structures due to infection with pyogenic bacteria. "It has been reported that aureus peptidoglycan promotes osteoclast formation through TLR2-mediated activation of the nuclear factor kappa-B (NF-κB)/nuclear factor of activated T cells 1 (NFATc1) signaling pathway, causing bone destruction and the formation of osteomyelitis." (PMID 39301021, 2024). "The present study aimed to elucidate the NFATc1 and BCL6 mediated osteoclastic regulation and activity in MRONJ (BP) compared to osteoradionecrosis (ORN) and osteomyelitis (OM) and normal jaw bone." (PMID 30832685, 2019).
parasite infection (2 papers, 2012 to 2018). "to activate NFATc1 that was among the molecules inhibited after parasite infection." (PMID 30327482, 2018). "Furthermore, several other mechanisms that induce intracellular Ca2+ influx as well as activation of NFATc1 and bradykinin B2 receptor can be activated by this parasite infection." (PMID 21869919, 2012).
sarcoma (2 papers, 2021 to 2022). A usually aggressive malignant neoplasm of the soft tissue or bone. "Some characteristically methylated genes are associated with bone lesions or osteocyte activity, but detailed investigation of their relationship with sarcoma is still lacking, for example, PHOSPHO1 and NFATC1." (PMID 36619306, 2022).
serous ovarian carcinoma (2 papers, 2019 to 2022). "NFATC1 overexpression in high-grade serous ovarian carcinomas was associated with poor overall survival and of early relapse." (PMID 35631574, 2022). "Furthermore, NFATC1 overexpression in high-grade serous ovarian carcinoma is an independent prognostic factor of poor overall survival and early relapse." (PMID 30901947, 2019).
T-cell lymphoma (2 papers, 2015 to 2018). "NFATc1 nuclear localization or dephosphorylation of both NFATc1 and NFATc2 were found in primary tumor samples and cell lines, derived from a patient with an aggressive T-cell lymphoma." (PMID 25866806, 2015).
triple-negative breast carcinoma (2 papers, 2015 to 2025). An invasive breast carcinoma which is negative for expression of estrogen receptor (ER), progesterone receptor (PR), and human epidermal growth factor receptor 2 (HER2). "Calcium-sensitive transcription factor NFATc1, which is important for cell migration, was shown to be frequently activated in triple negative breast cancer (TNBC) biopsy tissues." (PMID 39436410, 2025).
type 2 diabetes (2 papers, 2017 to 2025). "Interestingly, the NFATC1 gene is less methylated and more expressed in individuals with lower socioeconomic status which is a known risk factor for increased inflammation that can lead to pathologies such as type II diabetes." (PMID 28545453, 2017).
acute lymphoblastic leukaemia (1 paper, 2016). "Further, in the pTCR-positive DN3 cells, a threshold level of NFATc1 activity is vital in facilitating T-cell differentiation and to prevent Notch3-induced T-acute lymphoblastic leukaemia." (PMID 27312418, 2016).